DPF1 (double PHD fingers 1)
Description:
May have an important role in developing neurons by participating in regulation of cell survival, possibly as a neurospecific transcription factor. Belongs to the neuron-specific chromatin remodeling complex (nBAF complex). During neural development a switch from a stem/progenitor to a postmitotic chromatin remodeling mechanism occurs as neurons exit the cell cycle and become committed to their adult state. The transition from proliferating neural stem/progenitor cells to postmitotic neurons requires a switch in subunit composition of the npBAF and nBAF complexes. As neural progenitors exit mitosis and differentiate into neurons, npBAF complexes which contain ACTL6A/BAF53A and PHF10/BAF45A, are exchanged for homologous alternative ACTL6B/BAF53B and DPF1/BAF45B or DPF3/BAF45C subunits in neuron-specific complexes (nBAF). The npBAF complex is essential for the self-renewal/proliferative capacity of the multipotent neural stem cells. The nBAF complex along with CREST plays a role regulating the activity of genes essential for dendrite growth (By similarity).
Synonyms: BAF45B; NEUD4; neuro-d4; SMARCG1
Tractability: PROTAC: UniProt records ubiquitination sites on it; its protein half-life has been measured.
Gene: Protein-coding gene on chromosome 19 (38,211,006 to 38,229,714, reverse strand). Ensembl gene ENSG00000011332.
Subcellular location: Cytoplasm; Nucleus
Subcellular location (Human Protein Atlas): Cytosol; Nucleoplasm; Mitochondria
Pathways (Reactome):
Chromatin organization: Formation of neuronal progenitor and neuronal BAF (npBAF and nBAF); Formation of the canonical BAF (cBAF) complex
Developmental Biology: Regulation of MITF-M-dependent genes involved in pigmentation
Gene expression (Transcription): Regulation of endogenous retroelements by Piwi-interacting RNAs (piRNAs)
Gene Ontology:
Molecular function: sequence-specific double-stranded DNA binding; transcription coregulator activity
Biological process: apoptotic process; chromatin remodeling; nervous system development; positive regulation of cell differentiation; positive regulation of double-strand break repair; regulation of DNA-templated transcription; regulation of G0 to G1 transition; regulation of G1/S transition of mitotic cell cycle; regulation of mitotic metaphase/anaphase transition; regulation of nucleotide-excision repair; regulation of transcription by RNA polymerase II
Cellular component: chromatin; nBAF complex; nucleoplasm; cytoplasm; nucleus
Genetic constraint (gnomAD): Loss-of-function variants: 15 observed, 55.71 expected, observed/expected ratio (o/e) 0.27, 90% interval 0.18 to 0.41. The upper end of that interval is the gene's LOEUF score, 0.41, which puts it in group 1 of 6, group 1 being the genes least tolerant of losing a copy. Missense variants: 344 observed, 507.77 expected, observed/expected ratio (o/e) 0.68, 90% interval 0.62 to 0.74. Synonymous variants: 216 observed, 213.8 expected, observed/expected ratio (o/e) 1.01, 90% interval 0.9 to 1.13.
Homologues: Orthologues: chimpanzee DPF1 (100% identical), macaque DPF1 (100% identical), pig DPF1 (99% identical), mouse Dpf1 (98% identical), rat Dpf1 (98% identical), guinea pig DPF1 (90% identical), dog DPF1 (90% identical), tropical clawed frog dpf1 (86% identical), zebrafish dpf1 (82% identical), Drosophila melanogaster d4 (41% identical), Caenorhabditis elegans dpff-1 (34% identical), Drosophila melanogaster tth (3% identical). Paralogues in human: DPF3 (69% identical), DPF2 (60% identical), KAT6A (22% identical), KAT6B (20% identical), RSF1 (20% identical), KAT7 (17% identical), KAT5 (15% identical), KAT8 (14% identical), PHF10 (8% identical).
Diseases named in the same sentence as DPF1 in open-access papers:
DPF1 is named in the same sentence as 8 diseases in open-access papers, as found by Europe PMC text mining. Sharing a sentence is not in itself a finding about the gene and the disease. The quoted sentences say what the papers report.
glioblastoma (1 paper, 2017). The most malignant astrocytic tumor (WHO grade IV). "Collectively, our results indicate that DPF1 and DPF3a are potential therapeutic targets for glioblastoma." (PMID 28420882, 2017).
prostate carcinoma (1 paper, 2014). A carcinoma that arises from epithelial cells of the prostate gland. "By inspection, we also identified at least 10 additional transcription factors within 500 kb of 9 other GWAS loci, that are also reasonable candidates for contributing to prostate cancer risk: SOX13, ZFP36L2, ATOH8, DLX1 & DLX2 (same locus), GATA2, SKIL, SP8, ASCL2, and DPF1." (PMID 24497837, 2014).
cancer (5 papers, 2012 to 2023). A tumor composed of atypical neoplastic, often pleomorphic cells that invade other tissues. "A bioinformatics analysis revealed that DPF1, which is a member of the neuron-specific chromatin remodeling complex, is among the most consistently overexpressed genes in various cancers analysed by the TCGA consortium." (PMID 29287594, 2017). "We demonstrate here that the paralogous cancer-related minor SWI/SNF subunits DPF1, -2, -3; BCL7A, -B, -C; and SS18 and SS18L1 reside in BAF-class human SWI/SNF complexes and, that PHF10 marks PBAF SWI/SNF complexes." (PMID 22442726, 2012).
tumor (2 papers, 2017 to 2022). "The serum-induced differentiation of GICs downregulated the endogenous expression of DPF1 and DPF3a, and the shRNA-mediated knockdown of each gene reduced both sphere-forming ability and tumor-forming activity in a mouse xenograft model." (PMID 28420882, 2017).
DPF1 also shares sentences with these, for which no sentence is quoted: adenocarcinoma (1 paper); autism (1); neuroendocrine carcinoma (1); Zika Virus Infection (1).